MAP3K1 (mitogen-activated protein kinase kinase kinase 1)
Description:
Component of a protein kinase signal transduction cascade. Activates the ERK and JNK kinase pathways by phosphorylation of MAP2K1 and MAP2K4. May phosphorylate the MAPK8/JNK1 kinase. Activates CHUK and IKBKB, the central protein kinases of the NF-kappa-B pathway.
Synonyms: MEKK 1; MAPKKK1; MEKK; MEKK1; SRXY6
Tractability: Small molecule: a drug acting on it is in phase 2 or 3 trials; a high-quality ligand is known; it belongs to a druggable protein family. PROTAC: it is named in the literature on targeted protein degradation; ubiquitination databases record sites on it; a small molecule that binds it is known.
Target class: Enzyme; STE protein kinase STE11 family; Kinase; STE protein kinase group; Protein Kinase
Gene: Protein-coding gene on chromosome 5 (56,815,538 to 56,896,152, forward strand). Ensembl gene ENSG00000095015.
Subcellular location (Human Protein Atlas): Cytosol
Pathways (Reactome):
Immune System: FCERI mediated MAPK activation; MyD88 cascade initiated on plasma membrane; MyD88:MAL(TIRAP) cascade initiated on plasma membrane; TRAF6 mediated NF-kB activation; TRAF6 mediated induction of NFkB and MAP kinases upon TLR7/8 or 9 activation
Gene Ontology:
Molecular function: protein binding; protein kinase activity; protein kinase binding; protein serine/threonine kinase activity; ubiquitin protein ligase activity; MAP kinase kinase kinase activity; ATP binding; protein serine kinase activity; zinc ion binding
Biological process: cellular response to mechanical stimulus; Fc-epsilon receptor signaling pathway; MAPK cascade; protein phosphorylation; cell surface receptor signaling pathway
Cellular component: tight junction; cytosol
Genetic constraint (gnomAD): Loss-of-function variants: 33 observed, 124.31 expected, observed/expected ratio (o/e) 0.27, 90% interval 0.2 to 0.35. The upper end of that interval is the gene's LOEUF score, 0.35, which puts it in group 1 of 6, group 1 being the genes least tolerant of losing a copy. Missense variants: 1,584 observed, 1,752.1 expected, observed/expected ratio (o/e) 0.9, 90% interval 0.87 to 0.94. Synonymous variants: 686 observed, 637.45 expected, observed/expected ratio (o/e) 1.08, 90% interval 1.01 to 1.15.
Cancer hallmarks: proliferative signalling (promotes); invasion and metastasis (promotes); escaping programmed cell death (promotes); escaping programmed cell death (promotes or suppresses)
Homologues: Orthologues: chimpanzee MAP3K1 (99% identical), macaque MAP3K1 (98% identical), pig MAP3K1 (95% identical), dog MAP3K1 (94% identical), mouse Map3k1 (90% identical), rat Map3k1 (90% identical), rabbit MAP3K1 (85% identical), guinea pig MAP3K1 (84% identical), tropical clawed frog map3k1 (74% identical), zebrafish map3k1 (64% identical). Paralogues in human: MAP3K19 (15% identical), PAK3 (9% identical), PAK2 (9% identical), PAK6 (9% identical), PAK1 (9% identical), PAK5 (9% identical), PAK4 (8% identical), MAP3K14 (7% identical), SLK (6% identical), TNIK (6% identical), MINK1 (6% identical), TAOK1 (6% identical), and 23 more.
Diseases named in the same sentence as MAP3K1 in open-access papers:
MAP3K1 is named in the same sentence as 129 diseases in open-access papers, as found by Europe PMC text mining. Sharing a sentence is not in itself a finding about the gene and the disease. The quoted sentences say what the papers report.
breast cancer (166 papers, 2007 to 2025). A primary or metastatic malignant neoplasm involving the breast. "Protein-truncating variants in established susceptibility genes BRCA2, BRCA1, CHEK2, PALB2, ATM and MAP3K1 were associated with a risk of breast cancer, while BARD1 and ATRIP met exome-wide significance for the first time." (PMID 41044259, 2025). "MAP3K1 has been implicated in promoting cell proliferation and invasion in various cancers, including breast cancer and colorectal cancer, suggesting its potential oncogenic role in GC." (PMID 39901302, 2025). "Exome-wide analysis has recently additionally identified rare variants in MAP3K1 (MIM: 600982) to be associated with breast cancer risk." (PMID 40073867, 2025). "Since the prevalence of MAP3K1 mutation in HR+/HER2– breast cancer is less than 20%, the immunosuppressive tumor microenvironment cannot be entirely attributed to MAP3K1 mutation." (PMID 39531335, 2024). "MAP3K1 mutation is closely correlated with immune microenvironment heterogeneity in HR+/HER2– breast cancer." (PMID 39531335, 2024). "MAP3K1 was identified as a causative gene by searching for the susceptibility alleles of breast cancer." (PMID 39443331, 2024). "Our multi-omics analysis of a large cohort of patients revealed that MAP3K1 mutation was associated with an immunosuppressed microenvironment in HR+/HER2– breast cancers." (PMID 39531335, 2024). "To date, a plethora of studies have reported the influence of MAP3K1 rs889312 polymorphism on the prognosis of cancers, including distant disease‐free survival, disease‐free survival, or overall survival of breast cancer, colorectal cancer, gastric cancer." (PMID 36560873, 2023). "In BCCuS-low group, the mutation frequency of PIK3CA, CDH1, MAP3K1 up-regulated, these genes have been reported as tumor suppressor in breast cancer." (PMID 36699089, 2022). "Previous studies have focused on the association between MAP3K1 and hormone-related cancers such as breast cancer." (PMID 36510163, 2022). "Analysis in humans indicated that MAP3K1 is the gene in the corresponding region (human chromosome 5q11.2) with the greatest influence on risk of breast-cancer development." (PMID 34388197, 2021). "Genome-wide association studies also found that the MAP3K1 gene is associated with human breast cancer." (PMID 33806889, 2021). "Previous study also suggested that PIK3CA and MAP3K1 alterations imply luminal A status in breast cancer and are associated with clinical benefits from PI3K inhibitors." (PMID 32391377, 2020). "Among the previously reported loci, FGFR2 on chr10q26.13 and TOX3-CASC16 on chr16q12.1 are the two most significant associated breast cancer susceptible loci across different populations, followed by MAP3K1 on chr5q11.2 and CCDC170-ESR1 on chr6q25.1." (PMID 31757997, 2019). "Of note, we were unable to identify any ER+ breast cancer cell line within the Cancer Cell Line Encyclopedia19 with both genomic loss/inactivating mutations in MAP3K1 coincident with a PIK3CA mutation." (PMID 31552290, 2019). "This is a significant finding because frequent mutational inactivation of genes that encode JNK pathway components (e.g. MAP2K4 and MAP3K1) are detected in human breast cancer." (PMID 29856313, 2018). "Recently, MAP3K1 rs889312 has been identified as a low-penetrant risk factor for breast cancer, both for ER+ or ER− breast cancer." (PMID 30285756, 2018). "Inactivating mutations of BRCA1 and BRCA2 frequently occur in breast cancer as well, while unique mutations in GATA3, PIK3CA, and MAP3K1 are enriched in the luminal A subtype of breast cancer." (PMID 29753129, 2018). "In breast cancer, we also checked MAP3K1 mutation with the similar methods for “MAPKKK cascade” term." (PMID 29485617, 2018).
breast cancer (continued). "The frequent mutation of the JNK pathway in human breast cancer (including the genes MAP3K1, MAP2K4, and MAP2K7) implicates reduced JNK signaling in the etiology of mammary carcinoma." (PMID 29856313, 2018). "An important goal for future studies will be to directly test the effect of MAP2K4 and MAP3K1 gene mutation on breast cancer." (PMID 29856313, 2018). "The exception to this was PIK3CA and MAP3K1 in ER-positive tumors, in keeping with reported better relapse-free survival rates in primary breast cancers carrying PIK3CA mutations." (PMID 28810143, 2017). "The rs16886165 SNP, which is close to 3’ of the MAP3K1 gene, was foundassociation with breast cancer risk in White women." (PMID 27863437, 2016). "On the other hand, a previously unnoticed connection between the stress-induced JUN-kinase pathway and breast cancer emerged through the identification of recurrent mutations in MAP3K1 and MAP2K4 in luminal-ER+ tumors." (PMID 26561834, 2015). "The most significantly associated SNP, rs702681 (OR 1.06 [95%CI 1.04–1.08]; P 3.9×10−10), is located in the 3'UTR of MIER3, close to the known breast cancer susceptibility gene MAP3K1." (PMID 25390939, 2014). "This meta-analysis demonstrated that the rs889312 and rs16886165 SNPs in MAP3K1 were associated with increased breast cancer susceptibility." (PMID 24595411, 2014). "Future larger sample studies are necessary to clarify more exact associations between these SNPs in MAP3K1 and breast cancer in African descendants." (PMID 24595411, 2014). "The single-nucleotide polymorphism (SNP) rs889312 in MAP3K1 was identified to be associated with breast cancer risk by GWAS, with confirmation of the association in European ancestry population by another study." (PMID 24595411, 2014). "In a previous meta-analysis based on breast cancer, the MAP3K1 rs889312 allele C has been identified as a low-penetrant risk factor for developing breast cancer." (PMID 24759887, 2014). "Recently, several studies have demonstrated that certain MAP3K1 rs889312 genotypes are genetic susceptibility markers for hormone-related tumors such as breast cancer and are significantly associated with risk of these tumors." (PMID 24759887, 2014). "A GWAS conducted in subjects of European descendant reported that the minor allele of MAP3K1 rs16886165 was associated with increased risk of breast cancer under heterozygote codominant and homozygote codominant genetic models." (PMID 24595411, 2014). "Genome-wide association studies (GWAS) have demonstrated that the single nucleotide polymorphism (SNP) MAP3K1 rs889312 is a genetic susceptibility marker significantly associated with a risk of hormone-related tumors such as breast cancer." (PMID 24759887, 2014). "Using publicly available CGEMS GWAS data to validate significant findings (N = 1,145 cases, N = 1,142 controls), rs889312 near MAP3K1 was confirmed to be associated with breast cancer risk (P = 0.04, OR 1.15, 95% CI 1.01–1.30)." (PMID 23634849, 2013). "The single SNP we assayed in the region surrounding MAP3K1, rs889312, was associated with breast cancer risk (OR 1.24, 95% CI 1.06–1.44)." (PMID 23634849, 2013). "Common genetic variation in loci encoding for FGFR2 and MAP3K1 influences risk of breast cancer, and these genes were previously found to be somatically mutated in diverse neoplasias including breast cancer." (PMID 21124932, 2010). "Polymorphisms in or near TOX3, LSP1, HCN1, MAP3K1 and at 2q35 are less strongly associated with breast cancer risk than polymorphisms in FGFR2; the increased risks range from 4% to 20% with each risk allele." (PMID 19232126, 2009). "Heterozygote carriers and minor allele homozygote carriers for SNP rs889312 in the MAP3K1 gene were less likely to be lymph node positive at breast cancer diagnosis (P = 0.044) relative to major allele homozygote carriers." (PMID 17997823, 2007). "MAP3K1 is one of the most frequently mutated cancer genes in luminal breast cancer." (PMID 39531335, 2024).
breast cancer (continued). "Taken together, the results indicate that the combination of postbiotic Tyra with PD-1 inhibitor could be a therapeutic strategy for the MAP3K1 mutation subgroup in HR+/HER2– breast cancers." (PMID 39531335, 2024). "BCK1 has homology to mammalian Map3K1, which is implicated in breast cancer in humans." (PMID 36598488, 2023). "MAP3K1 mutations are more frequent in hormone-receptor-positive (HR+) breast cancer than in TNBC." (PMID 37761830, 2023). "MAP3K1 gene rs889312 polymorphism has been extensively studied in breast cancer." (PMID 36560873, 2023). "Consistently, MAP3K1 mutations were frequently observed in luminal A subtype of breast cancer." (PMID 34404765, 2021). "Also, the serine/threonine kinase mitogen-activated protein kinase kinase kinase 1 (MEKK1) is found to be frequently deregulated in cancer, with somatic missense or nonsense mutations and copy number loss frequently occurring in luminal breast cancer." (PMID 34251884, 2021). "On the other hand, rat chromosome 2q14 (which harbors Gpbp1, Map3k1 and Il6st) coincides with Mamtr3 (also known as Mcs1b or Mcs10), another mammary-cancer susceptibility QTL for which the COP allele confers resistance to chemically induced mammary carcinogenesis." (PMID 34388197, 2021). "We asked whether PAM50 subtyping of the PDXs, which has been applied to other tumor types outside of breast cancer, or the presence of genomic alterations in MAP3K1 or PIK3CA were associated with an improved response in vivo to PI3K inhibition." (PMID 31552290, 2019). "We hypothesized that loss of function of MAP3K1 would render ER+ breast cancer cells more sensitive to PI3K inhibition, potential explaining the patient outcome data." (PMID 31552290, 2019). "However, we instead found that breast cancers with MAP3K1/PIK3CA co-mutations exhibit a strong luminal A phenotype." (PMID 31552290, 2019). "Mutations in MAP3K1 in ER+ breast cancer may be associated with clinical benefit from combined inhibition of PI3K and ER, but we could not ascribe direct biological function therein, suggesting they may be a surrogate for luminal A status." (PMID 31552290, 2019). "However, the longest-responding patient, whose tumor harbored a MAP3K1 L380S mutation, was excluded in this analysis, despite the fact that this is a recurrent mutation in breast cancer (AACR GENIE data v4.1), suggesting it is a loss-of-function mutation." (PMID 31552290, 2019). "Whether reduced JNK activity caused by loss of MAP2K4 or MAP3K1 phenocopies the effects of compound JNK deficiency on breast cancer is unclear." (PMID 29856313, 2018). "In the GWAS study, MAP3K1 rs889312 was found to be associated with breast cancer risk." (PMID 28178648, 2017). "Our findings implicated that MAP3K1-targeting miRNA might be of important therapeutic merit in breast cancer management." (PMID 26759750, 2016). "Stratified analyses for MAP3K1 rs889312 polymorphism and breast cancer risk." (PMID 24595411, 2014). "Up to date, a number of studies have investigated the relationship between polymorphisms in MAP3K1 and breast cancer or its malignant phenotypes, whereas the results were inconsistent and inconclusive in populations of diverse ethnicities, especially among Asians and Africans." (PMID 24595411, 2014). "However, after replicating our results using the CGEMS GWAS data, only rs889312 from the region near MAP3K1 was associated with breast cancer risk." (PMID 23634849, 2013). "Although the relationship between estrogen levels and the SNP, MAP3K1 rs889312, remains unclear, we speculated that the C/C allele of MAP3K1 rs889312 may alter estrogen metabolism, and thus contribute to the progression of estrogen-dependent breast cancers, especially in premenopausal women." (PMID 28178648, 2017). "Using model 3 with k = 0.5, novel association genes at exome‐wide significance were identified for breast cancer, for example, MAP3K1." (PMID 39749474, 2025).
breast cancer (continued). "Notably, the immunological heterogeneity of HR+/HER2– breast cancer was related to mitogen-activated protein kinase kinase kinase 1 (MAP3K1) mutation and we validated experimentally that a MAP3K1 mutation could attenuate CD8+ T cell–mediated antitumor immunity." (PMID 39531335, 2024). "Two genes, MAP3K1 and FGFR2, in addition to being previously identified in breast cancer-associated genetic region in GWAS, are both classified as TIER1 cancer-driving genes in COSMIC Cancer Gene Census." (PMID 36703164, 2023). "Comprehensive genomic analyses revealed multiple alterations in MAP3K1 in different cancer types, including ER+ breast cancer." (PMID 37761830, 2023). "Two of them, MAP3K1 and FGFR2, are long-established risk genes for breast cancer mediated by both germline and somatic mutations." (PMID 36703164, 2023). "Previous studies reported that MAP3K1, as a serine-threonine kinase of the MAPK family, is frequently mutated in breast cancer and further influences Th1 polarization, leading to an immune-desert phenotype in BC." (PMID 36032140, 2022). "Among genes known to be related to human breast cancer, we previously reported the reduced expression of Pten (on 1q52, 0.53-fold), Pik3r1 (on 2q12, 0.61-fold), and Map3k1 (on 2q14, 0.75-fold) in mammary carcinomas of (SD×COP)F1 rats." (PMID 34388197, 2021). "One of the major oncogenic pathways in breast cancer is PI3K/AKT/mTOR, which is frequently upregulated by activating mutations in PIK3CA, MAP3K1, and AKT1, or inactivating mutations in PTEN, leading to increased growth signaling." (PMID 32926574, 2020). "Some of the listed genes already have functional data linking breast cancer CCVs and somatic point mutations to altered target gene expression, including ESR1, FGFR2, and MAP3K1." (PMID 31910858, 2020). "We found weak evidence for the association of risk variants rs294174 (ESR1), rs16886165 (MAP3K1), rs2214681 (CNTNAP2), rs4237855 (VDR), rs9594579 (RANKL), rs8183919 (PTGIS), rs2981582 (FGFR2), and rs1799950 (BRCA1) with sporadic breast cancer." (PMID 33126731, 2020). "Breast cancer cells harboring loss-of-function mutations in MAP2K4 (and MAP3K1) lack JNK-mediated activation of ErbB→CRAF→MEK1/2, and thus, are highly sensitive to MEKi35." (PMID 33122628, 2020). "In conclusion, male breast cancers constitute a heterogeneous disease, with a limited number of recurrently mutated genes (PIK3CA, GATA3, and MAP3K1) and numerous genes with pathogenic mutations at lower frequencies." (PMID 32210163, 2020). "In breast cancer cells, MAP3K1 activates MEK1/2 indirectly by stimulating an MAP2K4/MAP2K7→JNK pathway, which results in JNK-mediated positive feedback activation of ERBB RTKs that activate MEK1/235." (PMID 33122628, 2020). "It was previously reported that an inactivating mutation in MAP3K1, together with one of its downstream substrates encoded by MAP2K4, was more prevalent in the luminal A subtype of breast cancer." (PMID 32886682, 2020).